LRRK2 (leucine rich repeat kinase 2)
Diseases named in the same sentence as LRRK2 in open-access papers (continued):
Sharing a sentence is not in itself a finding about the gene and the disease.
Parkinson disease (continued). "Current estimates state that only 15% of PD patients carry a mutation in a known Parkinson's-related factor (e.g., LRRK2, PARK2/Parkin, PINK1, or SNCA)." (PMID 31192157, 2019). "Genetic variations within the LRRK2 gene are linked to a number of diseases, including Parkinson’s disease (PD), Crohn ́s disease and Hansen’s disease." (PMID 30872638, 2019). "In this regard, EFhd2 expression is increased in substantia nigra and was found associated with Lrrk2 in Parkinson’s disease." (PMID 31456657, 2019). "Collectively, our data demonstrates that the Parkinson’s disease-linked LRRK2 plays a crucial role in insulin-driven translocation and/or fusion of GLUT4-vesicles to the plasma membrane through the phosphorylation of Rab10." (PMID 30872638, 2019). "Mutations within Leucine-rich repeat kinase 2 (LRRK2) are associated with late-onset Parkinson’s disease." (PMID 30872638, 2019). "Although further work is needed to confirm some results, our data suggest that LRRK2 mutations are common in young-onset Parkinson’s disease (2.2%) and should be more regularly tested with appropriate genetic counselling." (PMID 31324919, 2019). "Several mechanisms have been proposed through which LRRK2 mutations can lead to Parkinson’s disease." (PMID 31920513, 2019). "Several mutations in leucine rich repeat kinase 2 (LRRK2) gene have been associated with pathogenesis of Parkinson’s disease (PD), a neurodegenerative disorder marked by resting tremors, and rigidity, leading to Postural instability." (PMID 29482628, 2018). "For example, the LRRK2 pathway linked to Parkinson’s disease and PD-1 signaling pathway in immuno-oncology were both significantly enriched during PTB infection." (PMID 29321020, 2018). "In experimental models, both in vivo and cellular, over-expression of Parkinson’s linked mutant leucine-rich repeat kinase 2 (LRRK2) is sufficient to induce neuronal death." (PMID 29472595, 2018). "Both loss of function and gain of function mechanisms have previously been proposed in LRRK2-associated Parkinson disease." (PMID 30571694, 2018). "Understanding these mechanisms is important because aberrant activity in the human Roco protein LRRK2 is associated with the pathogenesis of Parkinson’s disease." (PMID 30562929, 2018). "Rab38 has been implicated in frontotemporal dementia, and Parkinson’s disease (PD) via its interaction with leucine-rich repeat kinase 2 (LRRK2)." (PMID 30060521, 2018). "LRRK2/TPC action was also studied in fibroblasts derived from Parkinson's patients with the G2019S LRRK2 mutation." (PMID 29746898, 2018). "TPCs have been implicated in Parkinson's mediated by mutation in the LRRK2 gene which represents the most common cause of familial disease." (PMID 29746898, 2018). "We highlight the feasibility and practicability of using our assay in the clinical setting by studying a few patients with G2019S LRRK2 associated and sporadic Parkinson's as well as healthy controls." (PMID 29127255, 2018). "Tau neurotoxicity is further enhanced by expression of Lrrk carrying mutations homologous to Parkinson disease mutations in human LRRK2." (PMID 30571694, 2018). "Mutations in the leucine‐rich repeat kinase 2 (LRRK2) are associated with Parkinson's disease, chronic inflammation and mycobacterial infections." (PMID 29789389, 2018). "The LRRK2 gene is associated with both Parkinson’s disease and susceptibility to Mycobacterium leprae infection." (PMID 29321020, 2018). "Mutations in leucine‐rich repeat kinase 2 (LRRK2) are associated with a familial form of Parkinson's disease." (PMID 30260496, 2018). "Since LRRK2 mutations causing Parkinson disease can act in an autosomal dominant fashion, with both wild-type and mutant protein being present, we also included a mixture of wild-type and mutant recombinant proteins in a 1:1 ratio (mix) in our experiments." (PMID 30571694, 2018).
Parkinson disease (continued). "LRRK2 (leucine rich repeat kinase 2) has been a hot spot in the field of neurology as its mutations have been associated with Parkinson’s disease (PD)." (PMID 29482628, 2018). "LRRK2 not only constitutes a pleomorphic risk factor for developing Parkinson's, but also links familial and sporadic forms of the disease." (PMID 29127255, 2018). "LRRK2 encodes a large multi-domain enzyme and the prevalent G2019S mutation in Parkinson's affects its kinase domain enhancing catalytic activity." (PMID 29746898, 2018). "A haplotype located near the 5′ region of RAB29 is associated with Parkinson's and epistasis between Rab29 and LRRK2 gene variants has been demonstrated." (PMID 29212815, 2018). "Commonly occurring autosomal-dominant missense mutations within the LRRK2 (leucine-rich repeat protein kinase 2) protein are linked to Parkinson's disease." (PMID 29127256, 2018). "Mutations in leucine-rich repeat kinase 2 (LRRK2) are the most common cause of familial Parkinson disease." (PMID 30571694, 2018). "Here, we connect the pathobiology of two proteins associated with Parkinson disease through genetics and neuropathology in patients, leucine-rich repeat kinase 2 (LRRK2) and tau." (PMID 30571694, 2018). "Genetics and neuropathology link Parkinson disease with the microtubule-binding protein tau, but the mechanism of action of LRRK2 mutations and the molecular connection between tau and Parkinson disease are unclear." (PMID 30571694, 2018). "Leucine-rich repeat kinase 2 (LRRK2), originally identified as a causative genetic factor in Parkinson’s disease, is now associated with a number of pathologies." (PMID 30420654, 2018). "Other genetic studies of Parkinson's patient cohorts have found common variants within the LRRK2 and Rab29 genes that function coordinately to increase Parkinson's risk, as human genetic variants at these loci impact Parkinson's risk non‐additively." (PMID 29212815, 2018). "In future work, it would be very interesting to use the MJFF-pRAB10 phospho-specific antibody to investigate Rab10 phosphorylation levels in brain samples derived from LRRK2-mutated Parkinson's disease patients." (PMID 29127256, 2018). "In Parkinson disease, the most common mutation in the multidomain Leucine-rich repeat kinase 2 (LRRK2) protein leads to a hyper-activation of the kinase domain, resulting in hyper-phosphorylation of a number of Rab GTPase substrates including Rab5." (PMID 29469808, 2018). "The dosage sensitivity to wild-type Lrrk that we demonstrate in vivo and model biochemically is consistent with recovery of noncoding Parkinson disease risk variants at the LRRK2 locus, which presumably predispose to disease by modulating LRRK2 expression." (PMID 30571694, 2018). "Previous work indicated that Rab29, located within the PARK16 locus mutated in Parkinson's patients, operates in a common pathway with LRRK2." (PMID 29212815, 2018). "Since then, the majority of studies on LRRK2 have been focused on linking various point mutations in the various domains of LRRK2 with Parkinson’s disease, and the contribution of mutated LRRK2 protein to neuronal toxicity." (PMID 29472933, 2018). "Parkinson’s disease-linked mutations in LRRK2 enhance the kinase activity of the protein, therefore targeting LRRK2 kinase activity is a promising therapeutic approach." (PMID 29707617, 2018). "We recruited 13 healthy controls, 7 patients with sporadic Parkinson's, 5 patients with G2019 LRRK2 associated Parkinson's and 1 asymptomatic G2019S LRRK2 carrier." (PMID 29127255, 2018). "By including participants with LRRK2 G2019S associated Parkinson's, we anticipated to gain more insights into the effect size of LRRK2 kinase activity by means of Rab10 phosphorylation." (PMID 29127255, 2018). "Available data suggest that Parkinson's patients with VPS35[D620N] develop the disease at a younger age than those with LRRK2 mutations." (PMID 29743203, 2018).
Parkinson disease (continued). "The most common cause of the monogenic form of Parkinson’s disease known so far is the G2019S mutation of the leucine-rich repeat kinase 2 (LRRK2) gene." (PMID 28723952, 2017). "Mutations in the leucine-rich repeat kinase 2 (LRRK2) gene are the most common genetic cause of Parkinson’s disease." (PMID 28292328, 2017). "Mutations in the leucine-rich repeat kinase 2 (LRRK2) gene have been linked to inherited Parkinson's disease." (PMID 28289371, 2017). "A new study reveals the frequency of Leucine-Rich Repeat Kinase 2 (LRRK2) mutations associated with Parkinson’s disease (PD) in Latin Americans." (PMID 28649619, 2017). "In North African populations, G2019S mutation in LRRK2 gene, encoding for the leucine-rich repeat kinase 2, is the most prevalent mutation linked to familial and sporadic Parkinson’s disease (PD)." (PMID 28683740, 2017). "Missense mutations in the leucine-rich repeat kinase 2 (LRRK2) gene can cause late-onset Parkinson disease (PD)." (PMID 29166931, 2017). "Genetic studies identified mutations in the leucine-rich repeat kinase 2 (LRRK2) gene as a putative cause of inherited Parkinson's disease." (PMID 28912682, 2017). "We found that PAK6 kinase activity promotes neurite outgrowth through interaction with the Parkinson's disease (PD)-associated leucine-rich repeat kinase 2 (LRRK2)." (PMID 29311810, 2017). "3,3′,4,5′-THS played a significant role in treating Parkinson′s disease by suppressing the mutation of leucine-rich repeat kinase-2, the common cause of Parkinson′s disease." (PMID 29109374, 2017). "For instance, mutations in the PARK2 gene are classic examples of early-onset Parkinson’s disease, while mutations in the LRRK2 gene are the most frequent cause of late-onset autosomal-dominant Parkinson’s disease." (PMID 28261213, 2017). "The Parkinson’s disease‐associated LRRK2 protein is a multidomain Roco protein with GTPase activity." (PMID 29044096, 2017). "Mutations in Leucine-rich repeat kinase 2 (LRRK2) are associated with Parkinson's disease (PD) and, as such, LRRK2 is considered a promising therapeutic target for age-related neurodegeneration." (PMID 29311810, 2017). "They used ratio of ser-1292 LRRK2 to total LRRK2 to predict LRRK2 gene mutation status and Parkinson’s disease risk in carriers of LRRK2 gene mutation, and found that ser-1292 LRRK2 was closely related to Parkinson’s disease." (PMID 28851367, 2017). "Leucine-rich repeat kinase 2 (Lrrk2) has been implicated in the pathophysiology of Parkinson’s disease." (PMID 28120865, 2017). "Mutations in leucine-rich repeat kinase 2 (LRRK2) gene are the most common genetic cause for both familial and sporadic Parkinson’s disease to date with the G2019S LRRK2 (LRRK2 GS) being the most prevalent mutation." (PMID 28321439, 2017). "Mutations associated with leucine-rich repeat kinase 2 are the most common known cause of Parkinson’s disease." (PMID 28649611, 2017). "Rab29 localizes to the trans-Golgi network (TGN) and Rab29 knockout mice mimic a phenotype of LRRK2 knockouts – an age-associated lysosomal defect in the kidney." (PMID 29125462, 2017). "Autosomal-dominant mutations in the Park8 gene encoding Leucine-rich repeat kinase 2 (LRRK2) have been identified to cause up to 40% of the genetic forms of Parkinson’s disease." (PMID 28697798, 2017). "Mutations in Leucine Repeat Rich Kinase 2 (LRRK2), primarily located in codons G2019 and R1441, represent the most common genetic cause of Parkinson’s disease in European-derived populations." (PMID 28649619, 2017). "Mutations in leucine-rich repeat kinase 2 (LRRK2) are considered the most common genetic cause of familial Parkinson's disease." (PMID 27442895, 2017). "As it is reported, LRRK2 variant carriers share similar clinical and pathological features, including a wild range of onset ages, typical Parkinsonism presentation, and sensitivity to L-dopa therapy." (PMID 27668119, 2016).
Parkinson disease (continued). "Leucine-rich repeat kinase 2 (LRRK2) has been linked to several clinical disorders including Parkinson’s disease (PD), Crohn’s disease, and leprosy." (PMID 27424887, 2016). "Leucine rich repeat kinase 2 is a complex enzyme with both kinase and GTPase activities, closely linked to the pathogenesis of several human disorders including Parkinson’s disease, Crohn’s disease, leprosy and cancer." (PMID 27731364, 2016). "One such example is the LRRK2 protein kinase, a Ser/Thr kinase, which is activated by ‘hot spot’ autosomal-dominant R1441G or G2019S mutations found in ∼5% of Parkinson's disease sufferers." (PMID 27621483, 2016). "Activating mutations in leucine-rich repeat kinase 2 (LRRK2) are strongly associated with increased risk of Parkinson’s disease (PD)." (PMID 27503089, 2016). "Mutations in Park8, encoding for the multidomain Leucine-rich repeat kinase 2 (LRRK2) protein, comprise the predominant genetic cause of Parkinson's disease (PD)." (PMID 26824392, 2016). "Recent studies have linked certain single nucleotide polymorphisms in the leucine-rich repeat kinase 2 (LRRK2) gene with Parkinson’s disease (PD)." (PMID 26930193, 2016). "Parkinson's disease patients with LRRK2 mutations display abnormalities in presynaptic dopamine function as assessed by positron emission tomography." (PMID 26744332, 2016). "Mutations in six genes are known to cause Parkinson's disease (PD) (autosomal dominant: alpha-synuclein, LRRK2, VPS35 and autosomal recessive: Parkin, PINK1 and DJ1) and number of other genes are implicated." (PMID 27872751, 2016). "Our data indicate that Parkinson-related LRRK2 mutation R1628P leads to Cdk5 phosphorylation of LRRK2 at S1627, which would upregulate the kinase activity of LRRK2 and consequently cause neuronal death." (PMID 26930193, 2016). "Lrrk2, a gene linked to Parkinson’s disease, encodes a large scaffolding protein with kinase and GTPase activities implicated in vesicle and cytoskeletal-related processes." (PMID 26758690, 2016). "Autosomal dominant mutations that activate the leucine-rich repeat kinase 2 (LRRK2) cause inherited Parkinson's disease." (PMID 27474410, 2016). "The G2385R variant of the leucine-rich repeat kinase 2 (LRRK2) is strongly associated with Parkinson’s disease (PD) in Asian populations." (PMID 27330837, 2016). "A considerable amount of work has been done on this protein because mutations in LRRK2 cause familial and sporadic Parkinson’s disease (PD)." (PMID 28105308, 2016). "The mice had mutations in the gene encoding LRRK2 that are often found in human patients with Parkinson’s disease." (PMID 26824392, 2016). "Leucine-rich repeat kinase 2 (LRRK2) kinase activity is increased in several pathogenic mutations, including the most common mutation, G2019S, and is known to play a role in Parkinson’s disease (PD) pathobiology." (PMID 27658356, 2016). "Mutations in the protein LRRK2 have been associated with Parkinson's disease but little is still known about the basic functions of the protein in the brain." (PMID 27432119, 2016). "Mutations in the leucine-rich repeat kinase 2 (LRRK2) are linked to sporadic and familiar forms of Parkinson’s disease, and in Drosophila, mutated forms of its ortholog (dLRRK2) result in parkinsonism-like phenotypes." (PMID 27504085, 2016). "Leucine-rich repeat kinase 2 is a large protein with implications in genetic and sporadic causes of Parkinson's disease." (PMID 28119604, 2016). "Among them, the identification of several leucine-rich repeat kinase 2 (LRRK2) gene mutations has opened a novel scenario in Parkinson’s disease genetics." (PMID 26727265, 2016). "The G2019S LRRK2 mutation associated with Parkinson’s disease stimulated CaV2.1 channels to a greater degree than wt." (PMID 27242426, 2016). "One of these genes encodes the leucine-rich repeat kinase 2 (LRRK2) protein kinase where autosomal dominant mutations account for ∼1% of sporadic Parkinson's disease." (PMID 27474410, 2016).
Parkinson disease (continued). "In this report, we have executed a broad and in-depth analysis of the effects of LRRK2 mutation upon the mesostriatal dopamine systems using novel BAC transgenic rat models of Parkinson's disease." (PMID 26744332, 2016). "The most common LRRK2 mutation, G2019S, is found in about 4% of familial and 1–2% of apparently sporadic cases of Parkinson's disease; however, within certain populations, the R1441C mutation is more prevalent." (PMID 26744332, 2016). "Leucine‐rich repeat kinase 2 (LRRK2) is a causative gene for Parkinson's disease, but the physiological function and the mechanism(s) by which the cellular activity of LRRK2 is regulated are poorly understood." (PMID 26375402, 2015). "The upcoming tenth anniversary of the discovery of mutations in the leucine-rich repeat kinase 2 (LRRK2) gene in Parkinson's disease (PD) highlights numerous achievements in discovery and innovation." (PMID 25448543, 2015). "Based on the clinical similarities between IPD and Parkinson disease associated with LRRK2 gene mutations (LRRK2-PD), we aimed to characterize sleep in parkinsonian and nonmanifesting LRRK2 mutation carriers (NMC)." (PMID 26177462, 2015). "Here, we report that lysosomes are enlarged and aggregated in fibroblasts from Parkinson disease patients with the common G2019S mutation in LRRK2." (PMID 25416817, 2015). "Mutations in the most prominent member of the Roco family of proteins, leucine-rich repeat (LRR) kinase 2 (LRRK2), are the most frequent cause of late-onset Parkinson's disease (PD)." (PMID 26310572, 2015). "Our data thus suggest that TPC2 acts downstream of pathogenic LRRK2 to regulate trafficking within the endolysosomal system in a pathway of potential relevance to the pathology of LRRK2-mediated Parkinson disease." (PMID 25416817, 2015). "Mutations in LRRK2 are related to certain forms of Parkinson’s disease and, possibly, to the pathogenesis of Crohn’s disease." (PMID 26067490, 2015). "Mutations in the leucine-rich repeat kinase 2 (LRRK2) have been known to be a major genetic component affecting Parkinson's disease (PD)." (PMID 25821816, 2015). "Point mutations in LRRK2 are considered the most significant contributor to the pathogenesis of Parkinson’s disease, although the exact molecular mechanism has yet to be established." (PMID 26010658, 2015). "For instance, LRRK2 mutations are associated with Parkinsonism, ALS and dementia, leading to mitochondrial fragmentation, mitochondrial dysfunction and increased reactive oxygen species." (PMID 26300727, 2015). "Mutations in the leucine‐rich repeat kinase 2 (LRRK2)‐encoding gene are the most common cause of monogenic Parkinson's disease." (PMID 25899482, 2015). "Here, we present a detailed visual analysis strategy for functional protein networks, using the example of LRRK2, a protein mutated in Parkinson's disease (PD)." (PMID 25648416, 2015). "In Parkinson’s disease, causal mis-sense mutation in α-synuclein and mutations in Leucine-rich repeat kinase 2 (LRRK2, PARK8) genes have been identified." (PMID 25690002, 2015). "LRRK2 was identified in 2004 as the causative protein product of the Parkinson’s disease locus designated PARK8." (PMID 25737818, 2015). "The first description of a biologically relevant cellular phenotype of iPSCs indicated that generation of iPSCs carry the p.G2019S mutation in LRRK2 (the most common Parkinson’s disease-related mutation)." (PMID 25689424, 2015). "TPC2 is thus a potential drug target within a pathogenic LRRK2 cascade that disrupts Ca2+-dependent trafficking in Parkinson disease." (PMID 25416817, 2015). "Lrrk is the Drosophila ortholog of the human LRRK2, and dominant pathogenic mutations in this gene cause the most common familial forms and some sporadic cases of Parkinson’s disease." (PMID 26158631, 2015). "In the decade since then, genetic studies have revealed at least 6 dominant mutations in LRRK2 linked to Parkinson’s disease, alongside one associated with cancer." (PMID 25737818, 2015).